CD4 (CD4 molecule)
Diseases named in the same sentence as CD4 in open-access papers (continued):
Sharing a sentence is not in itself a finding about the gene and the disease.
sarcoidosis (253 papers, 2005 to 2026). Sarcoidosis is a multisystemic disorder of unknown cause characterized by the formation of immune granulomas in involved organs. "Apart from non-necrotizing granulomas, another immunological hallmark of sarcoidosis is a polarized inflammatory response towards CD4-positive T helper cells." (PMID 41328180, 2025). "In summary, increased baseline proportions of circulating PD-1+CD4+ Tm cells significantly associated with good FVC response to prednisone in patients with sarcoidosis." (PMID 38715030, 2024). "The clonal amplification of CD4+ T-cells, typical of sarcoidosis, indicates that a pathogenic antigen contributes to the development of the disease." (PMID 39598118, 2024). "We aimed to investigate the distribution of CD4+ T-cell subpopulations in sarcoidosis patients and its potential associations with clinical disease activity and a radiographic fibrotic phenotype." (PMID 37520566, 2023). "Reduction of active CD4+ T cells in lung tissue and normalization of IL-2 levels are associated with spontaneous clinical resolution of sarcoidosis." (PMID 37062818, 2023). "In BAL samples from sarcoidosis patients, however, the highest expression of CD4 and CD8 was associated with alveolar lymphocytosis, indicating that the disease was active at the time of diagnosis." (PMID 36835481, 2023). "In this study, we aimed to investigate the distribution of CD4+ effector and regulatory T-cell subpopulations in sarcoidosis patients in more detail and analyze their association with disease activity and radiographic phenotype." (PMID 37520566, 2023). "Quantitative levels defined by cell concentrations of BAL cells and CD4+/CD8+ ratio were evaluated together with genetic variants associated with sarcoidosis in 692 patients with extensive clinical data." (PMID 36824606, 2023). "Although lymphocytosis and normal neutrophil and eosinophil levels are frequent in the lavage of sarcoidosis patients, the diagnostic value of such findings is under debate; a similar situation is reported for CD4/D8 ratio." (PMID 36672683, 2023). "TGF-β1–driven induction of αE expression on CD4+ T cells has been reported to be reduced in sarcoidosis patients carrying a genetic polymorphism in the promoter of the ITGAE gene tagged by the rs2981 single nucleotide polymorphism." (PMID 34561227, 2021). "The pathogenesis of sarcoidosis is associated with CD4 + T Cell activation, and secretion of cytokines including interferon-γ, tumor necrosis factor (TNF)-α, and transforming growth factor-β." (PMID 33539409, 2021). "In conclusion the results in this study indicate that Vα2.3 can be an additive diagnostic marker to the CD4/CD8-ratio for sarcoidosis." (PMID 32111204, 2020). "Despite the low diagnostic accuracy of BAL for sarcoidosis, the presence of increased CD4/CD8 >3.5, in addition to a typical radiological picture and clinical context, is a feature specific enough to justify refraining from a biopsy." (PMID 32962242, 2020). "CD4/CD8 ratio and CD103+CD4+/CD4+ ratio appear to be useful diagnostic biomarkers to support the diagnosis of sarcoidosis, while disease severity can be predicted and monitored by a correlation between KL-6 and CD4+/CD8+ ratio." (PMID 32760396, 2020). "Studying the CD4+ T-cell subgroup that express Vα2.3, we found particularly in LS patients a strong association with the diagnose and a capacity to separate sarcoidosis from controls." (PMID 32111204, 2020). "As suspected by the accumulation of CD4+ T cells in the BAL of sarcoidosis subjects, the dominant genetic associations in sarcoidosis are linked to HLA." (PMID 32256501, 2020). "Some studies have shown lymphocytosis and elevated CD4/CD8 ratio in bronchoalveolar lavage fluid in patients which has been associated with a diagnosis of sarcoidosis." (PMID 33218322, 2020). "While the CD103+CD4+/CD4+ appears to be a useful diagnostic tool in sarcoidosis caution should be taken with the interpretation of this ratio." (PMID 32760396, 2020).
sarcoidosis (continued). "ROC curves for the CD4/CD8-ratio showed a high diagnostic capacity in both the complete patient group with sarcoidosis (AUC 0.89, p < 0.0001) and in patients with LS (AUC 0.92, p < 0.0001)." (PMID 32111204, 2020). "The BALF CD103+CD4+/CD4+ ratio below a cutoff point of 0.45 was associated with a better diagnostic performance for sarcoidosis, even in cases with a CD4+/CD8+ ratio < 3.5." (PMID 31466346, 2019). "Another study found a significant association between TLR9 expression and CD4+ lymphocytes in BAL of patients with sarcoidosis." (PMID 31182092, 2019). "Regulatory cells (Treg cells), which are defined as CD4+CD25brightFoxP3+ have been also implicated in the pathogenesis of sarcoidosis." (PMID 31182092, 2019). "An elevation of the CD4/CD8 ratio in the BALF is a well-known feature of sarcoidosis, which is characterized by granuloma formation associated with an increased number of activated T cells." (PMID 29401501, 2018). "For lipid mediators differing between controls and patients with sarcoidosis after false discovery rate adjustment (q < 0.05), associations with LS, CD4/CD8 ratio, chest radiograph stage, %FEV1 and %FVC were performed." (PMID 30509266, 2018). "In this study, we quantified the contribution of T-cells associated variants and of CD4/CD8 ratio in sarcoidosis phenotypes, Löfgren’s syndrome (LS) and non- Löfgren’s syndrome (non-LS)." (PMID 28717140, 2017). "Previous studies and the established diagnostic criterion of an elevated BALF CD4/CD8 ratio have hitherto assumed CD4+ T cells to be the driving force of disease in sarcoidosis." (PMID 28955342, 2017). "Further in vivo studies to determine if CD4+ T cell exhaustion is causal of sarcoidosis disease progression is warranted." (PMID 29234685, 2017). "Sarcoidosis CD4+ T cells exhibit loss of cellular function during progressive disease that follows the archetype of T cell exhaustion." (PMID 29234685, 2017). "We also demonstrated that genetic variants associated with CD8+ T-cell levels and CD4/CD8 ratio are key determinants in sarcoidosis, particularly in LS." (PMID 28717140, 2017). "This study, like many other studies pointed out the diagnostic value of CD4/CD8 in the diagnosis of sarcoidosis." (PMID 28245857, 2017). "Although the precise cause of inflammation in sarcoidosis remains an enigma, it is well-established that CD4+ T helper cells and macrophages play critical roles during granuloma formation." (PMID 24885153, 2014). "Active and persisting sarcoidosis was recently associated with a global CD4+ T cell subset dysfunction." (PMID 24339826, 2013). "A possible mechanism for this association is that anti-TNF-α therapies modulate a CD4+ Th1 cytokine response, key to the immunopathogenesis of sarcoidosis." (PMID 23320239, 2012). "IL-23 is a cytokine that is essential for the induction of IL-17 producing CD4+ T cells (Th17 cells) that were recently associated with granuloma formation in sarcoidosis by us and others." (PMID 22513006, 2012). "Sarcoidosis is associated with an increase in the number of alveolar T cells, and a shift to an increase in CD4 cells within these cells can be observed." (PMID 19242869, 2009). "The authors conclude that although sarcoidosis is associated with global CD4+CD25high regulatory T cell amplification, the cells are functionally insufficient to control local inflammation." (PMID 19046457, 2008). "Sarcoidosis is a granulomatous disease of unknown cause, secondary to an immune stimulus that generates a sustained activation of Th1 CD4 lymphocytes in the lung and other tissues, resulting in non-necrotizing granulomatous inflammation." (PMID 40821295, 2025). "In sarcoidosis, epithelioid cell granulomas are well-formed structures whose compact core consists of macrophages and cells originating from macrophages (epithelioid and giant cells) closely associated with CD4+ T-lymphocytes." (PMID 39598118, 2024).
sarcoidosis (continued). "However, the exact mechanisms by which specifically PD-1+CD4+ Tm cells and PD-1+ Tregs predispose to good prednisone sensitivity in sarcoidosis need to be elucidated." (PMID 38715030, 2024). "Increased ratios of CD4 to CD8 T cells in the BAL are associated with sarcoidosis." (PMID 37259300, 2023). "It is well known that CD4+ T cells and macrophages are the key cells of the inflammatory response in sarcoidosis, occurring in genetically susceptible individuals after the inhalation of unknown antigens, probably of mycobacterial nature." (PMID 37445947, 2023). "In sarcoidosis, the epithelioid-cell granulomas are well-formed structures whose compact core is composed of macrophages and macrophage-derived cells (epithelioid and giant cells), closely associated with CD4+ T lymphocytes." (PMID 37250639, 2023). "In addition, CD4 lymphocytes are abundant in the intestinal mucosa, as in sarcoidosis where they can be a pro-diagnostic element." (PMID 36421591, 2022). "Various studies have suggested that a high CD4+/CD8+ ratio combined with a low CD103+CD4+/CD4+ ratio could be a promising BAL diagnostic marker of sarcoidosis." (PMID 35629428, 2022). "It would seem paradoxical that PD-1 inhibitor ICIs could cause a DISR, as the PD-1 pathway was found to be upregulated in active sarcoidosis, and downregulation of PD-1 expression on CD4+ T cells was associated with spontaneous remission of sarcoidosis." (PMID 34203188, 2021). "Lymphadenopathy is the most common symptom of sarcoidosis while lymphocytosis occurs in the bronchoalveolar lavage fluid (BALF) in most patients with lung sarcoidosis and exhibit an elevated CD4/CD8 ratio which has been associated with a diagnosis of sarcoidosis." (PMID 34943912, 2021). "We set out to evaluate if an expansion of CD4+ Vα2.3+ T-cells per se in BALF could be used as an additional diagnostic tool for sarcoidosis." (PMID 32111204, 2020). "However, there is some controversy on the use of the CD103+CD4+/CD4+ ratio as a diagnostic tool for sarcoidosis." (PMID 32760396, 2020). "Sarcoidosis is a systemic granulomatous disease caused by CD4+ cell-dominant inflammation." (PMID 32228530, 2020). "The high CD4+/CD8+ ratio (>3.5) is considered to be highly specific (93–96%) for sarcoidosis and, when found in association with a typical clinical manifestation, may support the diagnosis and obviate the need for confirmation by additional procedures." (PMID 31281552, 2019). "The clonality of CD4+ T cells that express distinct T-cell receptors in sarcoidosis supports an antigen-induced etiology, and epidemiological studies have identified environmental and occupational risk factors for sarcoidosis." (PMID 27203210, 2016). "Sarcoidosis, for example, appears to be associated with an exaggerated cellular immune response to an unknown antigen and CD4+ Th1 lymphocytes are important effectors of pulmonary injury in this disease." (PMID 17610738, 2007). "If quantitative alteration of CD4 T cells function is not responsible per se for this association with cryptococcosis, alteration of qualitative CD4 T cell function could be involved in the pathophysiology, but T cell dysfunction in sarcoidosis is poorly understood so far." (PMID 35425769, 2022). "The fact that interferon-γ and GM-CSF are known to be produced by CD4+ helper T cells to activate macrophages reinforce the plausibility of an altered CD4 T cells-macrophage crosstalk as a potential mechanism of increased susceptibility to cryptococcosis in sarcoidosis patients." (PMID 35425769, 2022). "Therefore, differential expression of CD103 on CD4+ T-cells could serve as a diagnostic marker for sarcoidosis." (PMID 32760396, 2020). "Thus, although medications that inhibit pathogenic CD4+ T-cells show some clinical benefit in sarcoidosis, a recent review suggested that the goal of future treatments should be to ultimately restore T-cell function since re-invigorated T-cell function corresponded with clinical resolution." (PMID 33036432, 2020).
sarcoidosis (continued). "The specificity of these pathogenic CD4+T cells in sarcoidosis are currently unknown." (PMID 32256501, 2020). "Collectively, these disorders are strongly linked to CD4 T-cell cell immunopathology including follicular helper T-cell germinal center support for autoantibody formation and Th1-type T-cells responses for delayed type IV immune hypersensitivity reactions in sarcoidosis." (PMID 31849945, 2019). "Thus, the aims of our study were to investigate whether the circulating subsets of CD4+ helper T cells were associated with sarcoidosis relapse and with its remission after retreatment." (PMID 26845566, 2016). "While overall cell interactions were reduced in sarcoidosis, there was a relative increase in CD4+ T cell interactions, indicating a potential shift in immune dynamics." (PMID 42273700, 2026). "There was a two-fold difference between the ratio of CD4/CD8 in sarcoidosis patients and in patients with other diseases." (PMID 40725075, 2025). "Next, to examine the frequencies and distribution of CD4+ T cell maturation subsets in different groups of patients with sarcoidosis, we analyzed CD45RA and CCR7 co-expression on Th cells." (PMID 41376646, 2025). "HP typically has higher lymphocytic predominance than sarcoidosis along with a normal CD4/CD8 ratio." (PMID 40364285, 2025). "Previous studies have pointed to possible oligoclonal responses in end‐organs of sarcoidosis patients, including CD4+ cells in lung and CD8+ T cells in cerebrospinal fluid." (PMID 40469525, 2025). "CD4 was considerably higher in sarcoidosis than in other diseases; meanwhile, CD8 was the lowest in sarcoidosis." (PMID 40725075, 2025). "In contrast, in acne-related sarcoidosis, a high recruitment of CD4+ lymphocytes is in accordance with previous studies, demonstrating the main role played by this specific lymphocyte subset." (PMID 40724901, 2025). "Bronchoalveolar lavage (BAL) CD4/CD8 ratio: An elevated CD4/CD8 ratio in BAL fluid is suggestive of sarcoidosis." (PMID 40927193, 2025). "Previous studies noted that patients with sarcoidosis have significantly elevated levels of memory CD4+CD45R0+ Th cells compared to controls, although other research did not observe these changes in peripheral blood." (PMID 41376646, 2025). "The main pathological mechanism of sarcoidosis involves antigen-presenting cells (such as macrophages and dendritic cells) that phagocytize antigens, leading to an abnormal immune response by CD4 + T cells." (PMID 39904950, 2025). "Sarcoidosis also produces a lymphocytic pattern with a markedly elevated CD4/CD8 ratio within the lymphocyte population." (PMID 40364285, 2025). "In contrast, the frequencies of Tfh1 within EM CXCR5+ CD4+ T cells were significantly lower in both groups of patients with sarcoidosis compared and healthy controls, while Tfh2 and Tfh17 cells were significantly elevated." (PMID 41376646, 2025). "Flow cytometry demonstrated an 89.1% population of CD3+ T lymphocytes, with a predominance of CD4+ cells, further solidifying the diagnosis of sarcoidosis." (PMID 40729241, 2025). "The pathophysiology of sarcoidosis involves activation of macrophages and CD4+ T lymphocytes, leading to increased production of tumor necrosis factor-alpha (TNF-α), interleukin-2 (IL-2), interferon-gamma (IFN-γ), and serum amyloid A protein." (PMID 40988789, 2025). "Sarcoidosis has long been considered a CD4+T cell/Th1–mediated disease as CD4+cells are central to the immunopathogenesis." (PMID 41197661, 2025). "For instance, the bronchoalveolar lavage fluid (BAL) of patients with sarcoidosis often shows an elevated CD4+/CD8+ T cell ratio." (PMID 40165483, 2025). "For instance, in sarcoidosis, the breadth and specificity of CD4(+) T-cell responses are determined by HLA DRB1-specific epitopes in individuals with sarcoidosis susceptibility." (PMID 41026325, 2025).
sarcoidosis (continued). "When comparing lymphocyte immunophenotypes between HP and sarcoidosis patients, significant differences in CD4, CD8, and CD4/8 were observed." (PMID 40725075, 2025). "Increased levels of MIG and CXCR3 were demonstrated in biopsy and BAL fluid samples of patients with sarcoidosis, which is correlated with the number of CD4+ and total lymphocytes." (PMID 38611622, 2024). "In line with a more severely exhausted phenotype, our data show a more impaired immune system in IPF than in sarcoidosis patients, as demonstrated by the highest CD4-, CD8-, and CD56-PD-1+ TIGIT+ cell percentages." (PMID 38540243, 2024). "Regarding T cells, in sarcoidosis, as in our study, reduced naive CD4+ cells, increased CD8+ cells, and consequently a reduced CD4+/CD8+ ratio and an increase in Tregs were also observed." (PMID 38891910, 2024). "A meta-analysis observed a sensibility of 0.7 and a specificity of 0.83 of the CD4/CD8 ratio for the diagnosis of sarcoidosis." (PMID 39062076, 2024). "CD4+ memory T cells and regulatory T cells from patients with sarcoidosis displayed an aberrant phenotype at baseline, compared to HCs." (PMID 38715030, 2024). "In progressive sarcoidosis, circulating CD4+ T cells display an exhausted phenotype with high PD-1+ proportions." (PMID 38715030, 2024). "Within sarcoidosis patients, the proportions of PD-1+ Tregs showed a positive correlation with the proportions of PD-1+CD4+ Tm cells (r = 0.68 p < 0.001), and an inverse correlation with CD25+CD4+ Tm cells (r = -0.53 p < 0.05)." (PMID 38715030, 2024). "Historically, in the bronchoalveolar lavage, a T lymphocytosis with a CD4/CD8 ratio greater than 3 to 4 has been considered an ancillary biomarker of acute sarcoidosis." (PMID 39062076, 2024). "The granuloma of sarcoidosis is a tightly formed conglomeration of macrophages and multinucleated giant cells, surrounded by a well-formed ring of CD4+ T cells interspersed with CD8+ T cells and an occasional B-cell." (PMID 38337432, 2024). "The abundance of current data indicates that sarcoidosis is a highly polarized Th1 response with a predominance of CD4+ lymphocytes and fewer CD8+ lymphocytes producing interferon-gamma." (PMID 38337432, 2024). "Proportions of circulating PD-1+CD4 central- and effector memory T cells in sarcoidosis were increased and these cells showed decreased proliferative capacity." (PMID 38715030, 2024). "Thepresence of lymphocytosis and an increased CD4+/CD8+ cell ratio of ≥3.5 inthe bronchoalveolar lavage fluid is characteristic of sarcoidosis with asensitivity of 54–80% and a specificity of 59–80%." (PMID 39077350, 2024). "The current study shows increased baseline proportions of circulating PD-1+CD4+ memory and regulatory T cells in patients with sarcoidosis and good initial FVC response to prednisone." (PMID 38715030, 2024). "Instead, CD4 Th1 cells are highly active within sarcoidosis-affected lungs (as measured by BAL) even though there is relative peripheral lymphopenia and anergy in circulating lymphocytes." (PMID 38165044, 2024). "CD4+ T cells in sarcoidosis display hallmarks of exhaustion, such as poor response to T cell receptor (TCR), increased apoptosis and sustained PD-1 (programmed cell death protein 1) upregulation, probably as chronic antigen stimulation." (PMID 39062076, 2024). "The bronchoalveolar lavage (BAL) fluid of patients with sarcoidosis typically shows an imbalance toward CD4+ T cells, with a demonstrated ratio of 4:1 between CD4+ and CD8+ T cells." (PMID 38611622, 2024). "Immunohistochemistry in sarcoidosis shows infiltration of CD4+ helper T cells inside the granuloma, whereas CD8+ cells are rarer." (PMID 39062076, 2024). "To elucidate treatment effects on PD-1 and CD25 surface expression on CD4+ Tm cells and Tregs in sarcoidosis, we compared baseline blood samples with paired samples at 3 and 12 months." (PMID 38715030, 2024).